MT-ATP8 (mitochondrially encoded ATP synthase membrane subunit 8)
Description:
Subunit 8, of the mitochondrial membrane ATP synthase complex (F(1)F(0) ATP synthase or Complex V) that produces ATP from ADP in the presence of a proton gradient across the membrane which is generated by electron transport complexes of the respiratory chain. ATP synthase complex consist of a soluble F(1) head domain - the catalytic core - and a membrane F(1) domain - the membrane proton channel. These two domains are linked by a central stalk rotating inside the F(1) region and a stationary peripheral stalk. During catalysis, ATP synthesis in the catalytic domain of F(1) is coupled via a rotary mechanism of the central stalk subunits to proton translocation (Probable). In vivo, can only synthesize ATP although its ATP hydrolase activity can be activated artificially in vitro (By similarity). Part of the complex F(0) domain.
Synonyms: ATP8; A6L; URFA6L; formerly MTATP8
Tractability: Small molecule: a structure with a bound ligand is known. Antibody: UniProt predicts a signal peptide or a membrane-spanning region. PROTAC: ubiquitination databases record sites on it.
Gene: Protein-coding gene on chromosome MT (8,366 to 8,572, forward strand). Ensembl gene ENSG00000228253.
Subcellular location: Mitochondrion membrane
Pathways (Reactome):
Metabolism: Formation of ATP by chemiosmotic coupling
Metabolism of proteins: Mitochondrial translation termination
Organelle biogenesis and maintenance: Cristae formation
Gene Ontology:
Molecular function: protein binding; proton-transporting ATP synthase activity, rotational mechanism; proton transmembrane transporter activity
Biological process: proton motive force-driven mitochondrial ATP synthesis; proton motive force-driven ATP synthesis; proton transmembrane transport
Cellular component: mitochondrion; proton-transporting ATP synthase complex; mitochondrial inner membrane; mitochondrial membrane
Gene-disease validity (ClinGen):
ClinGen rates the evidence that MT-ATP8 causes each of these diseases.
mitochondrial disease (mitochondrial): Limited.
Homologues: Orthologues: chimpanzee MT-ATP8 (94% identical), macaque ATP8 (53% identical), rat Mt-atp8 (49% identical), mouse mt-Atp8 (46% identical), pig ATP8 (44% identical), rabbit ATP8 (44% identical), guinea pig ATP8 (40% identical).
Diseases named in the same sentence as MT-ATP8 in open-access papers:
MT-ATP8 is named in the same sentence as 56 diseases in open-access papers, as found by Europe PMC text mining. Sharing a sentence is not in itself a finding about the gene and the disease. The quoted sentences say what the papers report.
cardiomyopathy (5 papers, 2014 to 2025). A disease of the heart muscle or myocardium proper. "“Mt-Atp8-CM” cardiomyocytes manifested enrichment in transcripts related to cardiomyopathies and neurological disorders known to be associated with cardiomyopathies and heart defects." (PMID 38110334, 2023). "Intriguingly, the overlapping region of MT-ATP6 and MT-ATP8 seems to be a hotspot for mutations causing cardiomyopathy indicating that human heart is vulnerable to the dysfunction of mitochondrial ATPase." (PMID 31152278, 2020).
Parkinson disease (3 papers, 2021 to 2023). A progressive degenerative disorder of the central nervous system characterized by loss of dopamine producing neurons in the substantia nigra and the presence of Lewy bodies in the substantia nigra and locus coeruleus. "Suspecting atypical Parkinsonism, a Wilson disease study and genetic tests of Charcot–Marie–Tooth (CMT), atypical Parkinsonisms (PARKs, GAB, DNAJC6, VPS13C, PINK, and LG), and atypical spinal–muscular atrophies (DYNC1H1, BICD, VAPB, GARS, DYNC1H1, mtATP6, and mtATP8) were carried out." (PMID 37510225, 2023).
COVID-19 (2 papers, 2023). A disease caused by infection with severe acute respiratory syndrome coronavirus 2. "Interestingly, we discovered that MT-ATP8 expression levels were associated with disease severity; in particular, the two COVID-19 patients receiving ECMO had near-zero MT-ATP8 expression compared to the no-ECMO patient and the healthy control." (PMID 36826040, 2023). "In particular, the naïve cells of COVID-19-infected subjects showed downregulation of MT-ATP8 and HLA-DQA1." (PMID 36826040, 2023). "Our analysis revealed a downregulation of FXYD, HLA-DRB1, and RPS20 in memory B cells; MTATP8 and HLA-DQA1 in naïve cells; RPS4Y1 in activated B cells; and IGHV3-73 in plasma cells in COVID-19 patients." (PMID 36826040, 2023). "Indeed, the two COVID-19 patients receiving ECMO showed lower MT-ATP8 expression, close to zero, compared to the no-ECMO patient and the healthy control." (PMID 36826040, 2023).
epilepsy (2 papers, 2021 to 2022). A brain disorder characterized by episodes of abnormally increased neuronal discharge resulting in transient episodes of sensory or motor neurological dysfunction, or psychic dysfunction. "While the 8490T>C mutation in MT-ATP8 gene was not previously reported in MS, different pathogenic mutations in MT-ATP8 gene were described in human disorders such as epilepsy, MIDD, brain pseudo-atrophy, episodic weakness and neurological disorders." (PMID 35130313, 2022).
congenital heart disease (1 paper, 2025). A heart disease that is present at birth. "MtDNA variants in the MT-ATP6 and MT-ATP8 genes have been indeed found in patients suffering from congenital heart disease as well as other multifactorial cardiovascular disorders." (PMID 39866453, 2025).
gout (1 paper, 2018). A condition characterized by painful swelling of the joints, which is caused by deposition of urate crystals. "When we categorized mutant alleles according to their positions in the mitochondrial genomes, 45 mutant alleles in patients with gout were located in the MT-ND5 region, followed-by the MT-CYB region (41 mutant alleles; 1 mutant allele was located in the overlapping MT-ATP6 and MT-ATP8 region)." (PMID 29976239, 2018). "In the non-gout controls, the MT-CYB region contained 69 alleles, followed by the MT-ND5 region (67 alleles; 3 mutant alleles were located in the overlapping MT-ATP6 and MT-ATP8 region)." (PMID 29976239, 2018).
Kearns-Sayre syndrome (1 paper, 2020). Kearns-Sayre syndrome (KSS) is a mitochondrial disease characterized by progressive external ophthalmoplegia (PEO), pigmentary retinitis and an onset before the age of 20 years. "One of them is ATP-synthase membrane subunit 8 (MT-ATP8), which has been implicated with infantile cardiomyopathy and Kearns-Sayre syndrome among other diseases." (PMID 32066524, 2020).
lung carcinoma (1 paper, 2025). "Interestingly, recent reports have shown that fragments of this gene, MT-ATP8, are present in both blood plasma and exosomes in particularly aggressive types of lung cancer, making it a potential candidate for liquid biopsy diagnostics." (PMID 39941116, 2025).
mild cognitive impairment (1 paper, 2023). "The mitochondrial coding and non-coding RNA are increased in the circulating extracellular vesicles in AD and mild cognitive impairment (MCI); the AD genes in the category of this study include MT-ND1-4,6, MT-ND4L, MT-ATP6, MT-ATP8, MT-CYB (or MT-CYBT), MT-CO1, and MT-RNR1." (PMID 36982253, 2023).
obsessive-compulsive disorder (1 paper, 2015). A disorder characterized by the presence of persistent and recurrent irrational thoughts (obsessions), resulting in marked anxiety and repetitive excessive behaviors (compulsions) as a way to try to decrease that anxiety. "The expression of other 5 protein-coding mitochondrial-encoded genes, MT-ND1, MT-ND5, MT-CO3, MT-ATP6, MT-ATP8, was found associated with the maternal psychopathology diagnosis of maternal obsessive compulsive disorder, maternal weight and with infant birth measures." (PMID 26418562, 2015).
skin inflammation (1 paper, 2021). "In both models, we showed that the m.7778G > T variant of the mt-Atp8 gene resulted in milder severity of skin inflammation." (PMID 33498298, 2021). "Additionally, the impact of the mt-Atp8 variant on neutrophil granulocytes (neutrophils) was assessed because this immune cell population plays a critical role in the effector phases of many inflammatory conditions, including skin inflammation." (PMID 33498298, 2021). "Thus, a diminished IL-17+ T cell population in the mt-Atp8 mutant mice likely contributed to the decrease in disease severity in both skin inflammation models in this study." (PMID 33498298, 2021).
cancer (3 papers, 2017 to 2025). A tumor composed of atypical neoplastic, often pleomorphic cells that invade other tissues. "The mitochondrial gene MT-ATP8 harbored the most significant variant in our predictive model of cancer." (PMID 39941116, 2025).
tumour (3 papers, 2019 to 2024). "Such tumor-exclusive variants were distributed in 13 genes, of which three (MT-ATP8, MT-ND4L and MT-TG) were only observed in this group." (PMID 31673122, 2019). "This notable number of variants that were exclusive to tumor was distributed in 13 genes, of which three (MT-ATP8, MT-ND4L and MT-TG) were only affected in this group." (PMID 31673122, 2019).
mitochondrial disease (1 paper, 2023). "In the mitochondrial MT-ATP8 gene, nine variants introducing the substitutions into subunit 8 of ATP synthase have been described to date in patients with mitochondrial diseases." (PMID 37340059, 2023). "Nine variants in the MT-ATP8 gene fragment specific for subunit 8 were described in patients suffering from mitochondrial diseases in the literature." (PMID 37340059, 2023).
MT-ATP8 also shares sentences with these, for which no sentence is quoted: Ataxia (4 papers); breast carcinoma (3); infertile (2); multiple sclerosis (2); neurodegenerative disease (2); neurological disorders (2); neuropathy (2); peripheral neuropathy (2); sterility (2); Alzheimer disease (1); amyotrophic lateral sclerosis (1); asthenozoospermia (1); autoimmune disease (1); autoimmune pancreatitis (1); bladder cancer (1); carcinosarcoma (1); cardiovascular disorder (1); coronary artery disease (1); diabetes (1); Encephalopathy (1); gastric tumor (1); heart failure (1); Huntington disease (1); Hypertension (1); hypertrophic cardiomyopathy (1); infection (1); Leber hereditary optic neuropathy (1); leprosy (1); male infertility (1); metabolic disorders (1).
A further 12 diseases each share a sentence with MT-ATP8 in 1 paper.